INS (insulin)
Diseases named in the same sentence as INS in open-access papers (continued):
Sharing a sentence is not in itself a finding about the gene and the disease.
Insulin resistance (continued). "Inadequate insulin supply, through inadequate dosing for maternal diet or insulin resistance, results in insufficient carbohydrate availability for cellular metabolism, provoking mobilisation of lipid and protein stores to meet fuel requirements." (PMID 37615689, 2023). "Significant improvements of serum insulin, homeostasis model assessment of insulin resistance (HOMA-IR), and GLUT4 levels were observed." (PMID 36625086, 2023). "Inflammation within adipose tissue can lead to an increased pro-inflammatory-to-anti-inflammatory macrophage ratio, potentially disrupting insulin signaling and contributing to insulin resistance." (PMID 38132296, 2023). "Data shows that PP1γ, on one hand, regulates neuronal insulin signaling and insulin resistance via AKT2-AS160-GLUT4-glucose uptake arm and AD-like phenomena via AKT2-GSK3β-Tau-NFT arm." (PMID 37085815, 2023). "Obese children tend to develop an early onset of puberty and have increased insulin production, which promotes the release of gonadotropins and decreases the level of sex hormone-binding globulin, contributing to insulin resistance." (PMID 37964223, 2023). "More specifically, excessive TNF-alpha promotes skeletal muscle insulin resistance by negatively regulating insulin signal transduction to glucose uptake." (PMID 37139450, 2023). "On the other hand, glucocorticoids, such as hydrocortisone (HC) and prednisolone, are recognised to induce insulin resistance and to some extent adversely alter insulin secretion." (PMID 37650517, 2023). "Insulin resistance (IR), a state of systemic insulin sensitivity decline in the body, is a key mechanism of glucose and lipid metabolism disorders." (PMID 38523869, 2023). "Iron depletion can ameliorate insulin resistance by augmenting the activity of insulin signaling through up-regulation of InR expression and activity." (PMID 37887373, 2023). "Two kinases displayed impaired insulin-activation in three or more insulin resistance models, ERK (CI, TNF, AA), and CDK5 (CI, TNF, MPQ, AA)." (PMID 36808134, 2023). "One of the most striking observations from these studies is that only a small fraction of the signalling changes seen in insulin resistance involved canonical insulin signalling proteins." (PMID 37248992, 2023). "The significant decrease observed in the insulin resistance index TyG after treatment is consistent with previous studies showing that liraglutide improves insulin sensitivity in T2D patients." (PMID 37143040, 2023). "Important insulin-independent signaling molecules like pAMPK and Sirt-1 promote insulin sensitivity and glucose metabolism, where they have been shown to affect insulin resistance-related variables in T2DM." (PMID 37512578, 2023). "To further show that metformin ameliorates insulin resistance, we found that the high glucose-induced impairment of insulin-induced relaxations in mouse mesenteric arteries was reversed by metformin." (PMID 37759984, 2023). "Insulin resistance and high insulin levels contribute to hepatocarcinogenesis through pathways such as PTEN/P13K/Akt and MAPKK." (PMID 37370771, 2023). "Given that HKII is regulated by insulin, its possible downregulation during insulin resistance leads to impairments in the autophagy pathway." (PMID 37876013, 2023). "In contrast, other studies showed that HSL mRNA and protein expression in adipose tissue were negatively correlated with fasting insulin levels and the HOMA-IR, and were higher in a subset of insulin sensitive adults than in insulin resistance participants." (PMID 37830580, 2023). "Somatostatin analogs of the first generation reduce insulin resistance but also the pancreatic secretion of insulin and glucagon." (PMID 37628857, 2023). "Repaired islet cells and increased insulin secretion, improved insulin resistance, and improved carbohydrate metabolism, amino acid metabolism and lipid metabolism." (PMID 36671814, 2023).
Insulin resistance (continued). "In another study, inhibition of C2C12 myoblast differentiation was observed in a palmitic acid-induced insulin resistance model, whereas glucose uptake activity and insulin sensitivity gradually increased during C2C12 myoblast differentiation." (PMID 38203642, 2023). "Available data indicate that plasma aminoadipic acid plays a role in the modulation of glucose levels through a compensatory response to hyperglycemia, resulting in increased insulin secretion in early insulin resistance." (PMID 38067430, 2023). "Serum glucose, triglyceride, leptin, insulin, and the insulin resistance index (HOMA-IR) were determined." (PMID 37242132, 2023). "While, among the common downregulated Pparg target genes, both Irs1 and Myc are involved in insulin signaling, revealing the Pparg-mediated insulin resistance in females during ovarian insufficiency." (PMID 36768630, 2023). "In conclusion, we identify that ZFYVE28 is involved in insulin signaling and mediates insulin resistance by promoting phosphorylated insulin receptor degradation." (PMID 37884540, 2023). "This study further highlighted the significantly higher insulin resistance in GS patients, as determined by the homeostasis model assessment, and their relatively lower insulin sensitivity indices." (PMID 38333726, 2023). "After 52 weeks of treatment with dorzagliatin, a numerally greater reduction in HbA1c of 1.03% from the baseline was observed in patients with T2DM, accompanied by significant improvement in insulin resistance and insulin secretion." (PMID 38179187, 2023). "Insulin resistance is the inability of the body’s cells to respond to insulin hormone signals, resulting in impaired glucose metabolism." (PMID 37508403, 2023). "Studies on animal models with insulin resistance provided evidence that baicalin effectively improves insulin sensitivity and thereby mitigates hyperglycemia." (PMID 38203600, 2023). "Assuming that there was an incretin effect of the GLP-1, it appears that the stimulation of insulin secretion was sufficient to overcome the insulin resistance in terms of the effects on the glucose concentrations." (PMID 37439859, 2023). "We assumed that aged GPR84-KO mice have peripheral insulin resistance; thus, a hyperinsulinemic-euglycemic clamp study to delineate the tissues responsible for decreased insulin sensitivity would be necessary." (PMID 37856216, 2023). "These β cell adaptations are particularly important when insulin demands or insulin sensitivity change, such as with pubertal growth, pregnancy, obesity, or insulin resistance." (PMID 37066881, 2023). "Metabolic abnormalities in carbohydrates, lipids, and proteins arise as a result of low levels of insulin to achieve adequate response or insulin resistance in target tissues." (PMID 36900596, 2023). "JNK1/2, another component of the MAPK family, has a substantial role on disrupting insulin action and exacerbating insulin resistance." (PMID 37375718, 2023). "Insulin resistance, defined as an impaired ability of insulin to induce glucose uptake in peripheral tissues resulting in hyperglycemia, is a hallmark of prediabetes and T2D." (PMID 37111216, 2023). "Insulin resistance can be discerned by the diminished glucose uptake rates in the principal insulin-responsive tissues, namely skeletal muscle, liver, and AT." (PMID 38235134, 2023). "A number of studies have reported that ROS and RNS can disrupt insulin signal transduction and have shown elevated levels of ROS in both obese animals and obese humans during insulin resistance." (PMID 37569463, 2023). "Prolonged use of insulin can lead to hyperinsulinemia, downregulation of insulin signaling and insulin resistance, which can increase glucose levels and oxidative stress." (PMID 37242426, 2023). "On the other hand, NAFLD contributes to the development and exacerbation of insulin resistance by releasing inflammatory cytokines and adipokines that interfere with insulin signaling pathways." (PMID 37374323, 2023).
Insulin resistance (continued). "Lastly, the presence of free radicals can impair the insulin signal transduction pathway, further exacerbating insulin resistance." (PMID 37893045, 2023). "Homeostasis model assessment of insulin resistance (HOMA-IR) was assessed according to the following formula: fasting insulin (microU/L) x fasting glucose (nmol/L)/22.5." (PMID 37208686, 2023). "Insulin resistance is characterised by the failure of insulin to stimulate glucose uptake by peripheral tissues or suppress hepatic glucose production." (PMID 36860368, 2023). "Insulin resistance further induces an increase in insulin release from a beta cell in order to keep the blood sugar level within a normal range." (PMID 37297501, 2023). "Here, we employed recent advances in the throughput and sensitivity of these technologies to analyze acute signaling responses to insulin in the context of adipose insulin resistance." (PMID 36808134, 2023). "Inhibition of insulin secretion, either due to intermittent insulin injection in type I diabetics or insulin resistance in type II diabetics, leads to hyperglycemia and chronic complications." (PMID 38137521, 2023). "Adipose insulin resistance (Adipo-IR), or the inability of adipose cells to respond properly to insulin, can lead to more fat getting stored in the liver, worsening NAFLD." (PMID 37814297, 2023). "A significant positive correlation of leptin with BMI, waist circumference, body fat, insulin, insulin resistance, total cholesterol, and HOMA-index was found in 107 women aged 67 to 78 years." (PMID 37371675, 2023). "In obesity, ectopic fat deposition in liver and muscle impairs insulin signaling in these cells and results in insulin resistance." (PMID 38026205, 2023). "Insulin resistance or insufficient insulin production in the body leads to the inability to maintain normal blood glucose levels." (PMID 37724233, 2023). "The use of bimoclomol and lipoic acid, inducers/co-inducers of HSPs, in obese rodents with insulin resistance was proven to improve insulin sensitivity." (PMID 36768170, 2023). "In the presence of insulin resistance, β cells secrete more insulin to maintain normal glucose control." (PMID 36936906, 2023). "Insulin resistance, which affects insulin-sensitive tissues, including adipose tissues, skeletal muscle, and the liver, is the central pathophysiological mechanism underlying type 2 diabetes progression." (PMID 36714242, 2023). "Genistein also declined plasma insulin and insulin resistance in SHR on a high NaCl diet and reduced plasma triglycerides and cholesterol in SHR." (PMID 37275572, 2023). "Previous studies have found acute and chronic inhibition of GSK3 in rodent models of insulin resistance improved insulin-stimulated glucose uptake into muscle." (PMID 36808134, 2023). "The MR Egger pleiotropy test indicated potential horizontal pleiotropy between ALM and insulin resistance (fasting insulin), but the MR PRESSO method provided consistent results with the IVW method after the exclusion of 28 potentially pleiotropic SNPs." (PMID 37403750, 2023). "Chronic insulin resistance leads to an increase in insulin production and in its bloodstream release which, in order to maintain normal glucose levels, causes a condition named hyperinsulinemia." (PMID 36902406, 2023). "Prior studies have shown that organisms can compensate for insulin resistance by increasing insulin output, while primary hyperinsulinemia leads to insulin resistance in target tissues." (PMID 36730473, 2023). "The link between impaired insulin actions and obesity is well-established: insulin resistance develops with increasing BMI and advanced age, particularly in women." (PMID 37658327, 2023). "The insulin secretion capacity of individual β-cells increases as a form of compensation in response to insulin resistance in target metabolic tissues." (PMID 37441495, 2023). "Even in healthy men, chronic smoking was connected to high insulin concentration and insulin resistance." (PMID 36975496, 2023).
Insulin resistance (continued). "The pathogenesis of obesity, insulin resistance, and abnormal insulin responses to food are all interlinked." (PMID 37819196, 2023). "As autophagy is usually suppressed by amino acids and insulin through the mTOR- or/and Akt-dependent pathways, suppressed lipophagy is observed in the liver of mice with insulin resistance and hyperinsulinemia induced by a high-fat diet (HFD)." (PMID 36677026, 2023). "Skeletal muscle insulin-resistance can explain the 50–60% reduction in whole-body insulin-stimulated glucose-uptake that is observed in pregnant women during late gestation." (PMID 37765126, 2023). "EPA and DHA supplementation improved metabolic (insulin, Homeostatic Model Assessment of Insulin Resistance [HOMA-IR], triglyceride [TG]/ high-density lipoprotein [HDL] ratio, TG, and arachidonic acid [AA]/EPA ratio) and tumor necrosis factor-alpha (TNF-α)." (PMID 37215211, 2023). "The results of this study showed that fasting insulin (p = 0.02) and insulin resistance (p = 0.014) were significantly reduced after 12 weeks of treatment with cinnamon as compared with the placebo group." (PMID 36797354, 2023). "Treatment with thymol decreased plasma glucose, insulin, insulin resistance, HbA1c, leptin, and adiponectin." (PMID 38029230, 2023). "Insulin sensitizers such as thiazolidinediones and metformin can positively affect the fibrinolytic system, partly mediated by insulin resistance alleviation and PAI-1 reduction." (PMID 37020596, 2023). "Insulin resistance is characterized by a reduction of the appropriate response to insulin stimulation, glycogen synthesis, and lipid oxidation." (PMID 37396948, 2023). "In this case, PDB extracts reduced insulin resistance and increased insulin sensitivity, thus reducing the secretion of FINS." (PMID 37849729, 2023). "Both drugs have improved insulin sensitivity so they can be very useful for patients with high insulin resistance, with glimepiride more recommended for patients with high level of IL-34." (PMID 37072577, 2023). "With regard the intercalated relation between insulin signaling and autophagy, hence, the interaction should be further studied in the setting of insulin resistance." (PMID 37876013, 2023). "This affected membrane dynamics and also altered insulin signaling, as measured by a decrease in protein kinase B (AKT) phosphorylation, which mediates insulin signaling, and this results in insulin resistance (IR), as in type 2 diabetes (T2D)." (PMID 36768583, 2023). "Insulin resistance, reduced insulin secretion, dyslipidemia, and β-cell degeneration lay the foundation of type 2 diabetes (T2D)." (PMID 37109458, 2023). "Studies have indicated that even at low doses, BPA can interfere with carbohydrate metabolism, impair insulin secretion and sensitivity, and contribute to the development of insulin resistance." (PMID 37570835, 2023). "Insulin resistance in peripheral organs stimulates insulin’s continuous release, leading to hyperinsulinemia and the exhaustion of pancreatic β-cells." (PMID 36904281, 2023). "Paralleling peripheral insulin resistance, striatal and hypothalamic activities monitored with fMRI in obese subjects were unresponsive to insulin in this protocol." (PMID 36979453, 2023). "While the influence (R2) of genes related to insulin production decreased (chromosome region 11p15.5 [Group 1], 32%; other genomic regions [Group 2], 34%), the influence of genes related to peripheral insulin resistance (Group 3) increased by 25%." (PMID 37291636, 2023). "They observed a significant insulin resistance using a euglycemic hyperinsulinemic clamp and at the end of the insulin signaling pathway insufficient translocation of GLUT4 transporters to the sarcolemma." (PMID 36967414, 2023). "This deficiency leads to significantly increased hepatic gluconeogenesis and hyperglycemia, which then stimulates abnormal insulin secretion, and finally develops insulin resistance." (PMID 37723622, 2023).
Insulin resistance (continued). "Conversely, type 2 diabetes (T2D) is attributed to insulin resistance and reduced insulin secretion." (PMID 37761009, 2023). "Numerous studies attributed to them insulin-mimetic properties with improving insulin resistance, antihiperglycemic and hepatoprotective activities." (PMID 36771031, 2023). "Finally, we identified a subgroup of genetic variants with a concomitant effect on insulin sensitivity and alterations in liver metabolism and inflammation, which could correspond to hepatic insulin-resistance processes, which we called the “hepatic-insulin resistance cluster”." (PMID 37790568, 2023). "It was previously shown that HOMA-B and HOMA-IR insulin resistance indices were related to the concentration of EVs and insulin cascade proteins in EVs." (PMID 37109070, 2023). "The term "insulin resistance" is commonly understood as a decrease in the response of insulin-sensitive tissues to insulin at its sufficient concentration, leading to chronic compensatory hyperinsulinemia." (PMID 36860209, 2023). "In this group, a mutation in the region of the Grb14 gene has been suggested to be what drives insulin resistance, given that Grb14 is an effector of insulin signaling and directly inhibits insulin receptor catalytic activity in vitro." (PMID 37217826, 2023). "Reduced brain insulin action (or brain insulin resistance) can be observed in obesity, T2D, aging, and AD, suggesting a possible link between metabolic and cognitive health." (PMID 37833898, 2023). "In the model, T2D emerges as a result of insulin resistance in combination with insufficient insulin secretion, which is secondary to impaired β-cell function and reduced β-cell mass." (PMID 38026205, 2023). "Third, FGF21 can reduce serum insulin and increase insulin sensitivity to protect against systemic insulin resistance." (PMID 36594101, 2023). "At 10 μg/L, each derivate demonstrated similar diabetogenic effects such as insulin resistance, decreased level of plasma insulin, and impaired glucose homeostasis, while hepatic gluconeogenesis and glycogenolysis were promoted." (PMID 38203409, 2023). "With excess nutrient intake, the pancreas produces more insulin in response to high circulating blood glucose levels that, overtime, can lead to insulin resistance." (PMID 37763308, 2023). "Nevertheless, in individuals with insulin resistance, these insulin-induced suppressive effects appeared to be diminished, ultimately resulting in increased VLDL synthesis and secretion." (PMID 38248815, 2023). "Previous studies found associations between SJL and glycaemic dysregulation, lower high-density lipoprotein, and higher triglycerides, insulin, insulin resistance, adiposity, and metabolic syndrome." (PMID 37528259, 2023). "This study discovered the binding and regulatory effects of Didymin on key proteins in the insulin signaling pathway, demonstrating its improvement on oxidative stress and insulin resistance in liver cells." (PMID 38115075, 2023). "Our results indicate that postnatal overfeeding is a contributing factor to impaired insulin signaling in skeletal muscle, whereas the presence of both overfeeding and hyperandrogenemia leads to more profound insulin resistance." (PMID 37371678, 2023). "There was a positive association between urinary phthalate (mainly MECPTP and DBP) levels and insulin resistance, considering the high amounts of plasma glucose, insulin, HOMA-IR, and HbA1c%." (PMID 37367903, 2023). "SOCS3, as a suppressor of cytokine signaling, is considered to promote insulin resistance by inhibiting insulin and leptin signaling during the inflammatory response." (PMID 36911682, 2023). "Previous genetic studies have largely focused on insulin resistance in the fasting state, where hepatic insulin action dominates." (PMID 37291194, 2023). "Lycium barbarum polysaccharides (LBPs) extracted from L. barbarum, markedly increased insulin secretion and insulin sensitizing activities to improve insulin resistance." (PMID 37497112, 2023).